SEZ6L2 (seizure related 6 homolog like 2)
Diseases named in the same sentence as SEZ6L2 in open-access papers (continued):
Sharing a sentence is not in itself a finding about the gene and the disease.
tumor (10 papers, 2020 to 2025). "Immunohistochemical validation confirmed higher expression of key TELscore genes, including GPX3 and SEZ6L2, in tumor tissues compared to adjacent normal mucosa." (PMID 40492114, 2025). "Upregulation of SEZ6L2 correlates with poor prognosis for CRCpts, and SEZ6L2 knockdown can impair tumor growth by promoting caspase‐dependent apoptosis in CRC." (PMID 35425715, 2022). "Our results indicated that SEZ6L2 was significantly up‐regulated in tumour tissues of patients with CRC compared with adjacent normal tissues." (PMID 32105413, 2020). "The IHC staining results demonstrated the low expression of SEZ6L2 in HCT116 tumour tissues from the shSEZ6L2‐1 and shSEZ6L2‐2 groups." (PMID 32105413, 2020). "The TUNEL assay indicated that the knockdown of SEZ6L2 significantly promoted the apoptosis of HCT116 tumour cells." (PMID 32105413, 2020). "While LARS2 and SEZ6L2 may contribute to immune suppression and tumor immune evasion, SOX7 appears to promote CD8+ T cell infiltration and antitumor immunity." (PMID 40230854, 2025). "Additionally, TELscore signature genes such as GPX3 and SEZ6L2 were highly expressed in tumor tissues compared to adjacent normal tissues." (PMID 40492114, 2025). "In CRC, knockdown of SEZ6L2 promotes the apoptosis of tumour cells, indicating that it might serve as a potential target for therapy." (PMID 38054820, 2023). "On the other hand, our results indicate that the SEZ6L2 protein is highly expressed in HCC tumor tissues, suggesting that it may be a potential therapeutic target." (PMID 32148567, 2020). "Our results indicated that the knockdown of SEZ6L2 efficiently inhibited the volume of HCT116 tumours by 52.3% (shSEZ6L2‐1) and 60.1% (shSEZ6L2‐2) (tumour volume: shNC group, 1138.6 ± 187.3 mm3 vs shSEZ6L2‐1 group, 543.2 ± 113.8 mm3 vs shSEZ6L2‐2 group, 453.8 ± 79.3 mm3)." (PMID 32105413, 2020). "The knockdown of SEZ6L2 impairs tumour growth by promoting apoptosis, which indicates that SEZ6L2 could be a potential therapy target for CRC." (PMID 32105413, 2020). "Furthermore, we showed that inhibition of SEZ6L2 via treatment with an anti-SEZ6L2 antibody reduced drug resistance and TS formation, suggesting that anti-SEZ6L2 antibody therapy may be an option for reducing tumor relapse after chemotherapy in LUAD." (PMID 33202873, 2020). "The analysis of LARS2, SEZ6L2, and SOX7 in the COAD tumor microenvironment suggests that these genes play significant roles in regulating CD8+ T cell infiltration and function." (PMID 40230854, 2025). "The results indicated that the knockdown of SEZ6L2 significantly promoted the expression of caspase 3 and cytochrome C in HCT116 tumours." (PMID 32105413, 2020). "Clinical data showed that high SEZ6L2 protein expression was correlated with tumor-node-metastasis (TNM) stages (P = 0.046), tumor number (P = 0.016), and tumor size (P = 0.029)." (PMID 32148567, 2020). "Interestingly, SEZ6L2 knock-out has been shown to promote apoptosis of COAD cells, affecting the ultimate size of xenografts in tumor models." (PMID 40230854, 2025). "These molecular alterations suggest that LARS2 and SEZ6L2 might contribute to COAD progression by promoting tumor growth and immune evasion, whereas SOX7 downregulation may facilitate tumor development by impairing tumor suppressive pathways." (PMID 40230854, 2025). "The correlation between SEZ6L2 and reduced CD8+ T cell presence in the tumor microenvironment indicates that it may contribute to immune escape mechanisms, thereby facilitating tumor growth and resistance to immunotherapy." (PMID 40230854, 2025). "In oncology, overexpression of SEZ6L2 serves as a negative prognostic marker in several tumor entities." (PMID 36310162, 2022). "Outside the neurological and psychiatric field, high SEZ6L2 gene expression in tumor tissue is a negative prognostic factor in various tumor entities." (PMID 36310162, 2022).
tumor (continued). "Although the precise control of immune infiltration by LARS2, SEZ6L2, and SOX7 in CD8+ T cells and tumor fibrotic process are not yet understood, the results are promising and justify additional research." (PMID 40230854, 2025). "In order to explore the reasons leading to the high expression of SEZ6L2 in HCC tissues, we analyzed 407 tumor samples versus 58 normal samples in HCC from the TCGA database." (PMID 32148567, 2020).
neurodevelopmental disorder (3 papers, 2009 to 2025). A behavioral and cognitive disorder with onset during the developmental period that involves impaired or aberrant development of intellectual, motor, or social functions. "Although less studied than SHANK3, SEZ6L2 has been implicated in neurodevelopmental disorders, and its dysregulation may contribute to the synaptic and behavioral abnormalities observed in ASD." (PMID 40330750, 2025). "The participants in our study with rare variants in ALDOA, KIF22, TAOK2 and SEZ6L2 did not present with ASD or neurodevelopmental disorders." (PMID 35330733, 2022).
SEZ6L2 also shares sentences with these, for which no sentence is quoted: cerebellar ataxia (3 papers); Cognitive impairment (3); COVID-19 (2); language delay (2); language disorder (2); retinopathies (2); autoimmune encephalitis (1); Disc Degeneration (1); neuroblastoma (1); Parkinsonism (1).